ZNF382 (zinc finger protein 382)
Description:
Functions as a sequence-specific transcriptional repressor.
Synonyms: KS1; FLJ14686
Tractability: PROTAC: ubiquitination databases record sites on it.
Gene: Protein-coding gene on chromosome 19 (36,604,817 to 36,634,114, forward strand). Ensembl gene ENSG00000161298.
Subcellular location: Nucleus
Subcellular location (Human Protein Atlas): Nuclear speckles
Pathways (Reactome):
Gene expression (Transcription): Generic Transcription Pathway; Regulation of endogenous retroelements by KRAB-ZFP proteins
Gene Ontology:
Molecular function: DNA-binding transcription factor activity; RNA polymerase II cis-regulatory region sequence-specific DNA binding
Biological process: regulation of transcription by RNA polymerase II; regulation of DNA-templated transcription
Cellular component: nucleus
Genetic constraint (gnomAD): Loss-of-function variants: 20 observed, 39.97 expected, observed/expected ratio (o/e) 0.5, 90% interval 0.35 to 0.73. The upper end of that interval is the gene's LOEUF score, 0.73, which puts it in group 2 of 6, group 1 being the genes least tolerant of losing a copy. Missense variants: 539 observed, 677.52 expected, observed/expected ratio (o/e) 0.8, 90% interval 0.74 to 0.85. Synonymous variants: 199 observed, 231.54 expected, observed/expected ratio (o/e) 0.86, 90% interval 0.76 to 0.97.
Homologues: Orthologues: chimpanzee ZNF382 (99% identical), macaque ZNF382 (98% identical), dog ZNF382 (90% identical), pig ZNF382 (84% identical), guinea pig ZNF382 (79% identical), rat Zfp382 (76% identical), mouse Zfp382 (76% identical), rabbit ZNF382 (74% identical), Drosophila melanogaster CG14442 (5% identical), Drosophila melanogaster CG14440 (4% identical). Paralogues in human: ZNF567 (61% identical), ZNF613 (41% identical), ZNF649 (37% identical), ZNF350 (36% identical), ZNF564 (32% identical), IKZF1 (15% identical), IKZF4 (15% identical), IKZF2 (14% identical), IKZF3 (13% identical), ZNF639 (13% identical), ZNF821 (9% identical).
Diseases named in the same sentence as ZNF382 in open-access papers:
ZNF382 is named in the same sentence as 25 diseases in open-access papers, as found by Europe PMC text mining. Sharing a sentence is not in itself a finding about the gene and the disease. The quoted sentences say what the papers report.
gastric cancer (4 papers, 2017 to 2023). A primary or metastatic malignant neoplasm involving the stomach. "In gastric cancer, the repression of ZNF382 resulted in an increase in tumor cell proliferation, migration, and invasion, and the inhibition of apoptosis." (PMID 37492743, 2023). "ZNF382 is down-regulated in multiple carcinoma types due to promoter methylation and functions as a tumor suppressor in gastric cancer." (PMID 33916522, 2021). "Dapper homolog 1 (DACT1), a disheveled partner in the planar cell polarity pathway, and a transcription regulator zink finger ZNF382 were found to be frequently silenced in gastric cancer cell lines and in primary gastric cancers via promoter hypermethylation." (PMID 28350359, 2017). "Overexpression of DACT1 or ZNF382 in silenced gastric cancer cell lines suppressed colony formation, proliferation and induced cell apoptosis." (PMID 28350359, 2017). "ZNF382 is also methylated and exhibits reduced expression in gastric cancer (GC) tissues." (PMID 33150179, 2020). "ZNF382 KRAB regulates EMT and functions as a tumor suppressor in gastric cancer." (PMID 33916522, 2021).
breast carcinoma (2 papers, 2014 to 2022). "As expected, several of the genes associated with top differentially methylated probes between these groups have been previously implicated in breast cancer, including SDC2, PBK, ALOX12B, DAG1, ZNF382, and FST." (PMID 35564499, 2022). "ZNF382 is a functional tumor suppressor that is frequently methylated in multiple carcinomas, including nasopharyngeal, esophageal, colon, gastric and breast cancer." (PMID 25319049, 2014). "ZNF382 has been shown to be frequently methylated in multiple primary tumors, such as nasopharyngeal, esophageal, colon, gastric and breast cancer." (PMID 25319049, 2014). "ZNF382 is a functional tumor suppressor frequently methylated in multiple carcinomas, including nasopharyngeal, esophageal, colon, gastric and breast cancer." (PMID 25319049, 2014).
esophageal squamous cell carcinoma (2 papers, 2019 to 2020). Esophageal squamous cell carcinoma (ESCC) is a type of esophageal carcinoma (EC) that can affect any part of the esophagus, but is usually located in the upper or middle third. "We further identified 406 promoter methylation target loci associated with patients survival, including known esophageal squamous cell carcinoma biomarkers, cg03234186 (ZNF154), and cg02587316, cg18630667, and cg05020604 (ZNF382)." (PMID 31379917, 2019). "In esophageal squamous cell carcinoma (ESCC), the expression of ZNF382 was inhibited due to aberrant promoter methylation and ZNF382 methylation correlated with the level of ESCC differentiation." (PMID 33150179, 2020).
acute lymphoblastic leukemia (1 paper, 2014). Leukemia with an acute onset, characterized by the presence of lymphoblasts in the bone marrow and the peripheral blood. "A genome-wide analysis of promoter associated CpG island methylation in acute lymphoblastic leukemia (ALL) has revealed DNA methylation of ZNF382 in primary ALL samples." (PMID 25319049, 2014).
Alzheimer disease (1 paper, 2025). A progressive, neurodegenerative disease characterized by loss of function and death of nerve cells in several areas of the brain leading to loss of cognitive function such as memory and language. "Our analysis identified several transcription factors with no previous association with Alzheimer's disease in astrocytes, including TOX3, MKX, ZBTB18, and ZNF382." (PMID 40656638, 2025).
bladder cancer (1 paper, 2021). "Moreover, with two other protein-coding genes, ZNF382 forms a prognostic signature that robustly predicts the outcome of bladder cancer patients." (PMID 34638319, 2021).
cervical tumors (1 paper, 2021). "ZNF382 was firstly identified as a direct repressor for several oncogenes (i.e., MYC, MITF, HMGA2, and CDK6) across distinct types of cancers, including lung, esophageal, colon, stomach, breast, and cervical tumors." (PMID 34638319, 2021).
Headache (1 paper, 2023). Cephalgia, or pain sensed in various parts of the head, not confined to the area of distribution of any nerve. "Recent GWAS analysis from the UK Biobank showed that the loss-of-function of ZNF10 and ZNF382 is associated with a high risk of headache and corneal hysteresis, respectively, although it is unclear whether these are direct consequences of derepressed expression of LINE-1 transcripts." (PMID 37680368, 2023).
hepatitis B (1 paper, 2021). "For instance, zinc finger protein 382 (ZNF382) is a potent tumor-suppressor and is down-regulated in hepatitis B-related HCC due to promoter methylation." (PMID 34150612, 2021).
hepatocellular carcinoma (1 paper, 2020). A malignant tumor that arises from hepatocytes. "ZNF382 is frequently downregulated by promoter methylation in HBV-associated hepatocellular carcinoma (HCC), and decreased expression of ZNF382 is closely linked to poor survival in patients with early HCC." (PMID 33150179, 2020).
idiopathic thrombocytopenic purpura (1 paper, 2014). "We then examined the methylation status of the ZNF382 promoter in pediatric AML samples and normal bone marrow (NBM)/idiopathic thrombocytopenic purpura (ITP) control samples." (PMID 25319049, 2014).
kidney cancer (1 paper, 2021). Primary or metastatic malignant neoplasm involving the kidney. "However, the role of ZNF382 in kidney cancer has not been determined yet." (PMID 34638319, 2021).
laryngeal squamous cell carcinoma (1 paper, 2021). A squamous cell carcinoma that arises from the larynx. "Recently, ZNF382 was reported as a component of an epigenetic signature that predicts the survival of laryngeal squamous cell carcinoma." (PMID 34638319, 2021).
leukemia (1 paper, 2014). A malignant (clonal) hematologic disorder, involving hematopoietic stem cells and characterized by the presence of primitive or atypical myeloid or lymphoid cells in the bone marrow and the blood. "MSP PCR assays were performed to detect the methylation status of the ZNF382 promoter in the 11 leukemia cell lines." (PMID 25319049, 2014). "To confirm the methylation of the ZNF382 promoter, we treated the leukemia cell lines with the demethylation reagent, 5-Aza." (PMID 25319049, 2014). "Our results revealed that the ZNF382 promoter was hypermethylated in 6 leukemia cell lines, including SHI-1, HL-60, THP-1, MV4-11, NB4 and K562 cells." (PMID 25319049, 2014). "In summary, our results demonstrated that the ZNF382 promoter was significantly methylated in leukemia cell lines." (PMID 25319049, 2014). "However, further studies focusing on the mechanisms responsible for ZNF382 downregulation in pediatric leukemia are required." (PMID 25319049, 2014). "Currently, the molecular function of ZNF382 in pediatric AML remains unknown and further investigations are required to elucidate the role of ZNF382 in pediatric leukemia." (PMID 25319049, 2014). "However, further studies focusing on the mechanisms responsible for ZNF382 methylation in pediatric leukemia are required." (PMID 25319049, 2014). "MSP PCR and BGS analysis revealed that ZNF382 was hypermethylated in leukemia cell lines." (PMID 25319049, 2014). "Furthermore, treatment with 5-aza-2′-deoxycytidine (5-Aza) upregulated ZNF382 expression in the selected leukemia cell lines." (PMID 25319049, 2014).
liver cancer (1 paper, 2021). An epithelial or non-epithelial malignant neoplasm that arises from the liver. "Furthermore, ZNF382 serves as a tumor suppressor in gastric and liver cancers, exerting its function through the inhibition of EMT and Wnt/β-catenin pathways, respectively." (PMID 34638319, 2021).
liver cirrhosis (1 paper, 2021). "ZNF382 was frequently downregulated by promoter methylation in HBV-related HCCs relative to HBV-infected liver cirrhosis tissues and decreased expression of ZNF382 was strongly correlated with poor survival in early-stage HCC patients." (PMID 34576022, 2021).
myeloid leukemia (1 paper, 2014). A clonal proliferation of myeloid cells and their precursors in the bone marrow, peripheral blood, and spleen. "In summary, these results demonstrate that the ZNF382 promoter is consistently methylated in human myeloid leukemia cell lines." (PMID 25319049, 2014). "In this study, we provide the first evidence of ZNF382 methylation in both AML cell lines and pediatric myeloid leukemia samples." (PMID 25319049, 2014).
oesophageal cancer (1 paper, 2018). "ZNF382 methylation was far more prevalent in oesophageal cancer tissues than in normal oesophagus tissues (p= 0.0023)." (PMID 29760376, 2018). "Higher levels of ZNF382 expression were associated with a better OS rate in oesophageal cancer patients (p= 0.028), suggesting that ZNF382 may be an independent prognostic factor in oesophageal cancer." (PMID 29760376, 2018).
pancreatic ductal carcinoma (1 paper, 2021). "Distinct methylation pattern of ZNF382 promoter might serve as a biomarker in pancreatic ductal carcinoma." (PMID 34638319, 2021).
tumor (19 papers, 2011 to 2025). "We hence focused on the 19q13.12 event, which resulted in the loss of a copy of ZNF382—a tumor suppressor and repressor of c-Myc42." (PMID 36424487, 2023). "Next, we analysed the relationship between ZNF382 methylation status and clinical features, and a significant association was found with tumour differentiation (χ2 test, p= 0.029)." (PMID 29760376, 2018). "Ectopic expression of ZNF382 in silenced tumor cells significantly inhibited their cloning and proliferation and induced apoptosis." (PMID 33150179, 2020). "Restoration of ZNF382 expression in silenced ESCC cells suppressed tumour cell proliferation and metastasis through inducing cell apoptosis." (PMID 29760376, 2018). "In summary, our findings demonstrate that ZNF382 functions as a bona fide tumour suppressor inhibiting ESCC pathogenesis through inhibiting the Wnt/β-catenin signalling pathway." (PMID 29760376, 2018). "ZNF382 had these mutations in six UCEC tumors and three COAD/READ tumors, and has been implicated as a tumor suppressor that is silenced in multiple carcinoma cell lines, including colon, cervical and gastric." (PMID 29953437, 2018). "Flow cytometry analysis of cell apoptosis was performed to evaluate the mechanisms of ZNF382 suppression of tumour cell growth." (PMID 29760376, 2018). "As previously demonstrated, the ectopic expression of ZNF382 in silenced tumor cells significantly inhibits clonogenicity, proliferation and induces apoptosis." (PMID 25319049, 2014). "It has been shown that the ectopic expression of ZNF382 in silenced tumor cells significantly inhibits their clonogenicity and proliferation, and induces apoptosis." (PMID 25319049, 2014). "Zinc finger protein 382 (ZNF382) has been suggested to be a tumor suppressor gene possibly regulated by promoter hypermethylation in various types of human cancer." (PMID 25319049, 2014). "Epigenetic inactivation of ZNF382 through promoter CpG methylation has been observed in multiple carcinoma cell lines and also in common primary tumours." (PMID 24294107, 2013). "In contrast to Th1Th17, Th1 cells expressed at superior levels several 10 genes of the zinc finger (ZNF) family, including the ZNF382, a tumor suppressor acting via the inhibition of the NF-κB signaling pathway." (PMID 24359430, 2013). "Expression of ZNF382 has been reported to be lost in cancers due to gene deletion or hypermethylation, but ZNF382 expression and tumor suppression are expected in hypomethylated states." (PMID 21876767, 2011). "Additionally, the methylation level of anaphase promoting complex (APC) and zinc finger protein 382 (ZNF382) are associated with the differentiation level of ESCC and exert a tumor-suppressive effect by inhibiting the WNT/β-catenin pathway." (PMID 40718833, 2025). "Here, we demonstrated the tumour suppressive effects of ZNF382 in ESCC cells." (PMID 29760376, 2018). "We further explored the mechanism of ZNF382 on tumour suppression of ESCC." (PMID 29760376, 2018). "These knockdown data confirmed that ZNF382 functions as a tumour suppressor in ESCC cells." (PMID 29760376, 2018). "ZNF382 functions as a tumor suppressor in multiple carcinomas." (PMID 25319049, 2014). "Similarly, ZNF382 is downregulated in multiple cancer types, including leukemia and the solid tumors of the head and neck, lung, esophagus, colon, stomach, cervix, and breast, and serve as a tumor suppressor." (PMID 34439859, 2021). "ZNF382 may also act by suppressing AP-1 signalling and repressing the expression of multiple oncogenes, thus exerting a pro-apoptotic role and inhibiting the proliferation of tumour cells." (PMID 24294107, 2013).
tumor (continued). "ZNF382 is one of KRAB domain zinc finger transcription factors (KZNFs) family member, which is involved in cell apoptosis and tumor suppression." (PMID 30185218, 2018). "Several ZFPs, such as ZNF217 and ZNF639, are oncogenic proteins, whereas other ZFPs, such as ZAC, ST18, ZNF382 and ZNF331, are tumour suppressors." (PMID 25714013, 2015). "In human cancers, some ZFPs, including ZAC, ST18, ZNF382 and ZNF331, function as tumour suppressors and are frequently inactivated by CpG methylation." (PMID 25714013, 2015). "We found that expression of MAGE I proteins, MAGE-A3 or MAGE-C2, relieved repression of a reporter gene by ZNF382, a KZNF with tumor suppressor activity." (PMID 21876767, 2011). "In the present work we demonstrate that MAGE I expression can regulate ZNF382, an important KZNF tumor suppressor, and can affect the ability of ZNF382 and KAP1 to bind and regulate a downstream target, the ID1 oncogene." (PMID 21876767, 2011). "ZNF382, also known as KS1, is a KZNF that was recently shown to be a tumor suppressor." (PMID 21876767, 2011). "ZNF382 is a tumor suppressor that is ubiquitously expressed in normal tissues, where it recruits KAP1 and causes chromatin compaction and suppression of several oncogenes including ID1." (PMID 21876767, 2011).
cancer (14 papers, 2011 to 2025). A tumor composed of atypical neoplastic, often pleomorphic cells that invade other tissues. "Meanwhile, NOL4, PAX6, TRIM58, and ZNF382 promoter methylation was also associated with the occurrence of many cancers." (PMID 31956659, 2019). "Zinc-finger protein 382 (ZNF382), as a member of the zinc-finger protein family, has been evidenced to be downregulated in several types of cancers." (PMID 34336665, 2021). "We recently identified ZNF382 as a novel KRAB-ZFP epigenetically inactivated in multiple cancers due to frequent promoter CpG methylation." (PMID 29760376, 2018). "We investigated the novel 19q13 KRAB-ZFP ZNF382, which is orthologous to rat KS1, and found that ZNF382 was highly expressed in normal tissues but frequently silenced in multiple carcinomas due to promoter CpG methylation." (PMID 29760376, 2018). "Our results clearly demonstrate the negative association between ZNF382 level and cancer stemness, which strongly corresponds to better overall survival of patients." (PMID 34638319, 2021). "Furthermore, functionally, ectopic expression of TET1 catalytic domain in cancer cell lines reactivated silenced tumor-suppressor genes (DLit2, ZNF382, HOXA9, and DKK1) and significantly suppressed clonogenicity of cancer cells compared to the catalytically dead mutant." (PMID 34209564, 2021). "We also examined ZNF382 protein expression in ESCC and paired adjacent non-cancer tissues by immunohistochemistry (IHC)." (PMID 29760376, 2018).
ZNF382 also shares sentences with these, for which no sentence is quoted: acute myeloid leukemia (1 paper); diffuse large B-cell lymphoma (1); endometrial carcinoma (1); esophageal cancer (1).